EMC2 (ER membrane protein complex subunit 2)
Description:
Part of the endoplasmic reticulum membrane protein complex (EMC) that enables the energy-independent insertion into endoplasmic reticulum membranes of newly synthesized membrane proteins. Preferentially accommodates proteins with transmembrane domains that are weakly hydrophobic or contain destabilizing features such as charged and aromatic residues. Involved in the cotranslational insertion of multi-pass membrane proteins in which stop-transfer membrane-anchor sequences become ER membrane spanning helices. It is also required for the post-translational insertion of tail-anchored/TA proteins in endoplasmic reticulum membranes. By mediating the proper cotranslational insertion of N-terminal transmembrane domains in an N-exo topology, with translocated N-terminus in the lumen of the ER, controls the topology of multi-pass membrane proteins like the G protein-coupled receptors. By regulating the insertion of various proteins in membranes, it is indirectly involved in many cellular processes (Probable).
Synonyms: KIAA0103; TTC35
Tractability: Small molecule: a structure with a bound ligand is known. Antibody: UniProt places it where antibodies can reach, with high confidence. PROTAC: UniProt records ubiquitination sites on it; ubiquitination databases record sites on it; its protein half-life has been measured.
Gene: Protein-coding gene on chromosome 8 (108,443,601 to 108,489,196, forward strand). Ensembl gene ENSG00000104412.
Subcellular location: Endoplasmic reticulum membrane
Gene Ontology:
Molecular function: membrane insertase activity; protein binding
Biological process: protein insertion into ER membrane by stop-transfer membrane-anchor sequence; tail-anchored membrane protein insertion into ER membrane
Cellular component: cytoplasm; EMC complex; endoplasmic reticulum; endoplasmic reticulum membrane; extrinsic component of endoplasmic reticulum membrane
Genetic constraint (gnomAD): Loss-of-function variants: 11 observed, 8.97 expected, observed/expected ratio (o/e) 1.23, 90% interval 0.76 to 1.84. That is too few expected variants to judge how well the gene tolerates losing a copy. Missense variants: 90 observed, 76.8 expected, observed/expected ratio (o/e) 1.17, 90% interval 0.99 to 1.4. Synonymous variants: 40 observed, 27.64 expected, observed/expected ratio (o/e) 1.45, 90% interval 1.12 to 1.84.
Homologues: Orthologues: chimpanzee EMC2 (100% identical), dog EMC2 (100% identical), macaque EMC2 (99% identical), mouse Emc2 (97% identical), rat Emc2 (97% identical), guinea pig EMC2 (96% identical), pig EMC2 (92% identical), rabbit EMC2 (92% identical), zebrafish emc2 (85% identical), tropical clawed frog emc2 (85% identical), Drosophila melanogaster EMC2A (41% identical), Drosophila melanogaster EMC2B (41% identical), and 1 more.
Diseases named in the same sentence as EMC2 in open-access papers:
EMC2 is named in the same sentence as 19 diseases in open-access papers, as found by Europe PMC text mining. Sharing a sentence is not in itself a finding about the gene and the disease. The quoted sentences say what the papers report.
breast carcinoma (5 papers, 2021 to 2025). "Here, we found that EMC2 expression is upregulated in breast cancer and is associated with poor overall survival." (PMID 40303285, 2025). "The frequency of EMC2 mutations in OV patients with “amplification” as the primary type was the highest (>15.41%), followed by breast cancer (10.33%)." (PMID 34956895, 2021). "Our previous work and bioinformatics analysis shows that the expression of Endoplasmic Reticulum Membrane Protein Complex Subunit 2 (EMC2) is up-regulated in breast cancer and is correlated with shortened overall survival of patients." (PMID 40303285, 2025). "In summary, our study revealed the mechanism by which EMC2 promotes breast cancer progression and identified EMC2 as a drug target for PDK1/AKT inhibition." (PMID 40303285, 2025). "In this study, we demonstrated that EMC2 was aberrantly upregulated in breast cancer tissues, significantly enhanced the proliferation and metastasis potential of tumor cells, and increased the sensitivity of tumor cells to PDK1/AKT inhibition." (PMID 40303285, 2025). "This study reveals the EMC2/USP7/ENO1/B-MYB protumorigenic axis in breast cancer and identifies EMC2 as a candidate target for PDK1/AKT inhibitory therapy." (PMID 40303285, 2025). "Silencing EMC2 significantly weaken the proliferation/metastasis potential of breast cancer in vitro and in vivo, but made tumor cell sensitive to PDK1/AKT inhibition." (PMID 40303285, 2025). "Silencing EMC2 significantly inhibited the proliferative and metastatic potential of breast cancer cells in vitro and in vivo." (PMID 40303285, 2025). "In summary, our study provides strong evidence for the mechanism of EMC2 in the development and progression of breast cancer, and highlights its significant potential as a target for PDK1/AKT inhibition." (PMID 40303285, 2025). "The results of our multivariate Cox regression analysis suggested that EMC2 can be used as an independent prognostic factor for breast cancer." (PMID 34956895, 2021). "On this basis, we used univariate and multivariate Cox regression to analyze the effect of EMC2 expression and other clinicopathological factors on breast cancer prognosis." (PMID 34956895, 2021). "The upregulation of EMC2 expression mediated by ncRNAs is related to poor prognosis and tumor immune infiltration in breast cancer." (PMID 34956895, 2021). "The LINC00665-miR-410-3p axis was identified as the most potential upstream ncRNA-related pathway of EMC2 in breast cancer." (PMID 34956895, 2021). "Our study is the first to reveal that EMC2 functions as a scaffold protein in breast cancer." (PMID 40303285, 2025). "In addition, although EMC2 was validated to a ferroptosis driver in the non small cell lung cancer cell, EMC2 was identified to be upregulated in esophageal adenocarcinoma and breast cancer." (PMID 35992146, 2022). "EMC2 expression in breast cancer tissue samples correlated with poor overall survival." (PMID 34956895, 2021). "In addition, we discussed the regulation of non-coding RNA (ncRNA) related to EMC2, including microRNA (miRNA) and long non-coding RNA (lncRNA), in breast cancer." (PMID 34956895, 2021). "All of these results collectively indicate that EMC2 has an important function in breast cancer and could become a new tumor prognostic biomarker." (PMID 34956895, 2021). "The results show that EMC2 expression had an important effect on breast cancer and could be used as an independent prognostic indicator; these findings were irrespective of the regression analysis used (univariate or multivariate)." (PMID 34956895, 2021). "In breast cancer, we find the amplification rate of EMC2 is 11% and the deep deletion rate is 0.1%." (PMID 34956895, 2021). "Therefore, the expression of EMC2 in breast cancer can have significant effects on factors such as tumor progression and even patient survival." (PMID 34956895, 2021).
breast carcinoma (continued). "Furthermore, clinical analyses based on public databases indicate that EMC2 may also function as a biomarker for reduced overall survival in breast cancer patients." (PMID 40303285, 2025). "However, the mechanism of EMC2 in breast cancer is yet to be elucidated." (PMID 40303285, 2025). "However, in breast cancer, the function of EMC2 is still unclear, and further research is needed." (PMID 34956895, 2021). "Drug sensitivity experiments revealed that EMC2 overexpression sensitizes breast cancer cells to PDK1 or AKT inhibition both in vitro and in vivo, whereas EMC2 silencing has the opposite effect." (PMID 40303285, 2025). "Although ferroptosis inducers hold promising potential in the treatment of breast cancer, the specific role and mechanism of the ferroptosis-related gene EMC2 in breast cancer have not been entirely determined." (PMID 34956895, 2021). "The results indicated that EMC2, G6PD, FLT3, IFNG, ANO6, and SLC1A4 were positively correlated with ferroptosis while CISD1, TP63, and BRD4 were negatively correlated with ferroptosis in breast cancer." (PMID 34222241, 2021).
breast invasive carcinoma (2 papers, 2021 to 2025). "In pan-cancer analysis, ISCU was obviously downregulated in breast invasive carcinoma, and EMC2 suffered the highest frequency of CNV." (PMID 40463869, 2025). "Finally, we determined the relationship between EMC2 expression and immune cell infiltration, immune cell biomarkers, or immune checkpoints in breast invasive carcinoma (BRCA)." (PMID 34956895, 2021).
esophageal cancer (2 papers, 2021 to 2025). A primary or metastatic malignant neoplasm involving the esophagus. "EMC2 has been identified as a predictive gene for esophageal cancer prognosis where higher expression indicates poorer prognosis as well." (PMID 40337509, 2025). "There were significant differences in the expression levels of EMC2 in BRCA, CHOL, esophageal carcinoma (ESCA), HNSC, KIRC, papillary renal cell carcinoma (KIRP), LIHC, LUSC, STAD, and THCA compared with the corresponding adjacent normal tissue controls." (PMID 34956895, 2021).
pancreatic cancer (2 papers, 2021 to 2023). "miRNA-143-5p has been implicated in the pathophysiology of cancer (including colon and pancreatic cancers) and schizophrenia-related disorders, and its effects on various target genes, such as EMC2, VWC2L, THY1, SGCZ, HIF1, and JDP2, among others, have been described." (PMID 37179125, 2023).
bladder urothelial carcinoma (1 paper, 2021). "For OS, a high EMC2 expression level showed unfavorable prognoses in bladder urothelial carcinoma (BLCA), BRCA, and uveal melanoma (UVM); however, KIRC patients with higher EMC2 expression showed a better prognosis." (PMID 34956895, 2021).
gastric cancer (1 paper, 2018). A primary or metastatic malignant neoplasm involving the stomach. "In the GA007 gastric cancer sample, we identified a fusion between the EMC2 gene exon 1 (NM_014673.4) and the RSPO2 exon 2 (NM_178565.4)." (PMID 30250044, 2018).
melanoma (1 paper, 2022). A malignant, usually aggressive tumor composed of atypical, neoplastic melanocytes. "In contrast, ALOX5, CISD1, ATP5MC3, NFS1, EMC2, ZEB1 are highly expressed in normal tissues, and they are related to the good prognosis of melanoma patients." (PMID 36313708, 2022).
paraganglioma (1 paper, 2021). A benign or malignant neoplasm arising from paraganglia located along the sympathetic or parasympathetic nerves. "For RFS, BLCA and HNSC patients with high EMC2 expression levels showed poor prognoses, while KIRC and pheochromocytoma and paraganglioma (PCPG) patients with high EMC2 expression levels had better prognostic survival." (PMID 34956895, 2021).
tumor (9 papers, 2015 to 2025). "The risk heatmap clearly shows EMC2 was up-regulated in high-risk group compared with the low-risk group, implying it is a tumor-promoting role." (PMID 33602233, 2021). "Taken together, our findings indicate that the ncRNA-mediated upregulation of EMC2 expression is associated with prognosis and poor tumor immune infiltration in of BRCA." (PMID 34956895, 2021). "The cBioPortal database was used to analyze the effect of EMC2 mutation on tumor prognosis." (PMID 34956895, 2021). "The high expression of EMC2 caused by its own gene amplification may also affect the expression of other genes, thereby improving the proliferation and drug resistance of tumor cells." (PMID 34956895, 2021). "We observed EMC2 mutations in different tumor samples in TCGA cohort." (PMID 34956895, 2021). "In this study, we revealed that ENO1 is protected from ubiquitin-mediated degradation by EMC2 29,30,46 and promotes tumor progression by stabilizing B-MYB mRNA." (PMID 40303285, 2025). "Through correlation, expression, and survival analyses, miR-410-3p was found to be the most significant miRNA tumor suppressor upstream of EMC2." (PMID 34956895, 2021). "Second, we used GEPIA2 to analyze the influence of EMC2 expression on tumor grading and found significant differences in COAD, ESCA, KIRC, and TCGT." (PMID 34956895, 2021). "To further explore the role of EMC2 in tumor immunity, we used the GEPIA database to determine the correlation of EMC2 expression with immune cell biomarkers in BRCA." (PMID 34956895, 2021). "The CpG sites of the EMC2 promoter were significantly methylated in the tumor samples compared to in the normal samples of most cancer types." (PMID 34956895, 2021). "EMC2 levels were significantly positively correlated with tumor immune cell infiltration, immune cell biomarkers, and immune checkpoint expression." (PMID 34956895, 2021). "Moreover, drug sensitivity assays revealed that high EMC2 expression sensitized tumor cells to PDK1/AKT inhibition." (PMID 40303285, 2025). "This indicates that tumor immune infiltration may partly account for EMC2-mediated carcinogenesis in BRCA." (PMID 34956895, 2021). "Our findings also indicate that EMC2 may exerts its carcinogenic effects by increasing tumor immune cell infiltration and immune checkpoint expression." (PMID 34956895, 2021). "However, it remains unclear whether EMC2 promotes tumor progression through ERAD-related mechanisms." (PMID 40303285, 2025). "Moreover, in future work, we intend to apply BX-795 and capivasertib to organoid or PDX models to further corroborate the conclusion that EMC2 sensitizes tumor cells to PDK1/AKT inhibition therapy, serving as a complement to existing in vivo and in vitro drug sensitivity experiments." (PMID 40303285, 2025). "When comparing the tumor tissues and the normal tissues, the expression of BRD4, EMC2, FLT3, and SIAH2 was upregulated in the tumor tissues." (PMID 40696656, 2025). "Most FRGs with gain of CNV exhibited significantly higher expression in BCa tumor tissues compared to normal adjacent tumor tissues or normal bladder tissues, such as FANCD2, EMC2, and TFRC." (PMID 35386202, 2022). "The protein levels of the EMC2 was significantly higher in tumor tissues compared with normal tissues based on the HPA database; the EMC2 protein levels were consistent with the RT-qPCR results." (PMID 34956895, 2021).
cancer (6 papers, 2021 to 2025). A tumor composed of atypical neoplastic, often pleomorphic cells that invade other tissues. "In this study, we performed expression, survival, and mutation analyses for EMC2 in various human cancers; to the best of our knowledge, this is the first study on these lines." (PMID 34956895, 2021). "In addition, we explored the potential relationship between EMC2 mutations and the clinical survival and prognosis among patients with different cancer types." (PMID 34956895, 2021). "Validation in the Cancer Cell Line Encyclopedia (CCLE) database confirmed that the expression of EMC2 was significantly higher in HPG cell lines compared to LPG cell lines." (PMID 40337509, 2025). "In conclusion, we clarified that EMC2 is highly expressed in multiple cancer types, including BRCA, and is positively correlated with unfavorable prognoses in BRCA." (PMID 34956895, 2021). "To explore the possible role of EMC2 in carcinogenesis, we first analyzed its expression in 33 human cancers." (PMID 34956895, 2021). "High expression levels of EMC2 were observed in most cancer types." (PMID 34956895, 2021). "The mRNA levels of CDKN1A, EMC2, FDFT1, HSPB, and MT1G, were analyzed comprehensively, and any correlations between the levels of mRNA of these five genes and pan-cancer prognosis were identified." (PMID 40432442, 2025). "The expression of mRNA of CDKN1A, EMC2, FDFT1, HSPB1, and MT1G in the TCGA and GTEx datasets were evaluated through the analysis of pan-cancer." (PMID 40432442, 2025). "CDKN1A, EMC2, FDFT1, HSPB1, and MT1G were assessed for their ability to serve as prognostic indicators in pan-cancer by utilizing the TCGA database." (PMID 40432442, 2025). "Owing to the lack of research on EMC2 in cancer, in this study, we aimed to perform a pan-cancer analysis of EMC2 expression using TCGA." (PMID 34956895, 2021).
EMC2 also shares sentences with these, for which no sentence is quoted: esophageal adenocarcinoma (1 paper); glioma (1); liver disease (1); mesothelioma (1); myxoid chondrosarcoma (1); non-small cell lung carcinoma (1); papillary renal cell carcinoma (1); pheochromocytoma (1); uveal melanoma (1).